CSF1R (colony stimulating factor 1 receptor)
Diseases named in the same sentence as CSF1R in open-access papers (continued):
Sharing a sentence is not in itself a finding about the gene and the disease.
tumor (continued). "Previous research has indicated PTPN11 could bind to the colony-stimulating factor receptor (CSF-1R) complex in response to CSF-1 stimulation in the tumor-associated macrophages to stimulate the Ras/Erk pathway, which can enhance tumor cell proliferation and migration." (PMID 35802774, 2022). "In fact, depletion of macrophages indiscriminately by drugs targeting CSF1 or CSF1R will cause substantial toxicity to normal tissues, instead, targeting downstream pro-tumor molecule mediated by CSF1, such as CXCL7, may be a better candidate for future drug development." (PMID 34789744, 2021). "Upon loading of an anti-colony stimulating factor-1 receptor targeted siRNA, M2NPs showed higher affinity to M2-like tumor-associated macrophages than to tissue-resident macrophages resulting in the elimination of M2 macrophage, thus decreasing tumor size in cancer bearing mice." (PMID 34683931, 2021). "For example, tumour‐entrained neutrophils (TENs) with CD11b+ (Ly‐6G)+ inhibited metastatic seeding, while tumour‐associated macrophages (TAMs), including metastasis‐associated macrophages (MAMs) with CD11b+, F4/80+ and CSF‐1R+, enhanced tumour progression and metastasis." (PMID 29930175, 2018). "However, there is some evidence that CSF-1R blockade may encourage accumulation of deleterious tumor-associated neutrophils." (PMID 28629162, 2017). "In addition, CSF1R blockade decreased tumor associated MDSCs and reduced tumor growth." (PMID 28149704, 2016). "In addition to the SDF-1/CXCR4 pathway enhanced by radiation-induced tumor hypoxia, the CSF-1/CSF1R signaling complex has also been recently implicated in recruitment of myeloid cells to growing tumors and in promoting the radiation-induced monocytic infiltration of tumors." (PMID 23882218, 2013). "Locoregional SC mediated release of biparatopic CSF-1R and PD-1 Nbs, reduced tumour growth by increasing T cell numbers, enhancing T cell activation, and by shifting the macrophage polarisation towards a pro-inflammatory phenotype." (PMID 41548537, 2026). "The distinct coexpression patterns of IL34 and CSF1R suggest their involvement in tumour progression, immune suppression, and potentially macrophage polarisation." (PMID 41362277, 2026). "Blocking the CSF1/CSF1R axis reduces M2-like TAMs infiltration and tumor metastasis, offering a promising strategy for metastatic CRC." (PMID 41639044, 2026). "Anti–CSF1R monoclonal antibodies have shown therapeutic benefit in multiple tumor types during clinical trials; combination treatment with chemotherapy can further augment their efficacy." (PMID 41426206, 2026). "CSF1R small interfering RNA (siRNA) and other inhibitors have successfully induced M1 repolarization in multiple tumor models, including colorectal cancer, high‐grade serous fallopian tube ovarian cancer, and follicular lymphoma." (PMID 41426206, 2026). "For example, tumor cell-secreted CSF-1 promotes the influx of monocyte precursors expressing the CSF-1 receptor (CSF-1R) and promotes their differentiation into M2 TAMs." (PMID 41590379, 2026). "Due to the central involvement of CSF-1/CSF-1R signaling in the attraction of TAMs to tumor sites and endorsement of M2 differentiation, CSF-1/CSF-1R targeting has become an appealing therapeutic strategy." (PMID 41590379, 2026). "Intracranial blocking of CSF1R led to a significant reduction in tumor growth and extended survival specifically in the TRPC group." (PMID 40661379, 2025). "Combined with CSF1R inhibitors, it reduced the number of tumor-infiltrating bone marrow cells and inhibited tumor growth." (PMID 40007537, 2025). "Surufatinib provides a biological basis for the synergistic effect of ICI and chemotherapeutic agents by inhibiting VEGFR, FGFR, and CSF-1R, exerting anti-angiogenesis and regulating the tumor microenvironment." (PMID 40463875, 2025). "We found that TMEM doorway tumor cells secrete CSF-1, which binds to the CSF-1R on TMEM doorway macrophages." (PMID 40646332, 2025).
tumor (continued). "CSF1R, binding to the ligands CSF-1, promotes the accumulation of TAMs with an immunosuppressive phenotype, mediating tumor progression and therapeutic resistance." (PMID 40404633, 2025). "Once recruited, CSF1R signaling promotes the differentiation of these precursors into immunosuppressive, M2-like TAMs, which secrete anti-inflammatory cytokines, support tumor angiogenesis and metastasis, and inhibit cytotoxic T cell activity." (PMID 40821795, 2025). "Accumulating evidence showed that, upregulated CSF-1 promotes the infiltration, survival, and metastasis of TAMs expressing CSF-1R in the tumor microenvironments, and blocking the CSF-1/CSF-1R signaling pathway can reduce immunosuppressive TAMs in tumors." (PMID 40007537, 2025). "The Sibson lab reported that the M279 monoclonal antibody against CSF-1R inhibited the growth of intracranially inoculated TNBC tumor cells, but the effect was predominantly due to infiltrating macrophages." (PMID 40760255, 2025). "Preclinical studies have suggested that the anti-tumor activity of CSF-1R blockade can be counteracted by chemokines-mediated recruitment of polymorphonuclear MDSCs, diminishing the overall efficacy." (PMID 40764998, 2025). "CSF-1R inhibition has been found to revert the polarization of TAMs and, as a consequence, reduce tumor proliferation." (PMID 40845580, 2025). "The inhibition of CSF1R presents a promising therapeutic strategy, as it selectively targets tumor-promoting macrophages while sparing antitumor macrophages." (PMID 41098573, 2025). "Tumor secretomes homogenize macrophage populations toward pro-tumor phenotypes, though ontogeny influences function, as CSF1R blockade affects brain microglia differently." (PMID 40995363, 2025). "CSF-1R also binds IL-34; elevated IL-34 and CSF-1R levels correlate with tumor progression and poorer survival." (PMID 40079009, 2025). "Targeting TAM-associated pathways, such as CSF-1R and CCR2, with AMG820 and PF-04136309 antibodies, respectively, can reprogram TAMs toward a pro-inflammatory M1 phenotype, supporting anti-tumor immunity." (PMID 39833954, 2025). "In summary, due to the crucial regulatory role of the CSF-1/CSF-1R signaling pathway in tumor development and fibrotic processes, inhibiting the CSF-1/CSF-1R signaling pathway seems to be a promising strategy for cancer treatment and fibrosis." (PMID 40007537, 2025). "A CSF-1R blocking antibody monotherapy achieved modest tumour growth inhibition by reducing TAMs and improving the ratio of CD8+ T cells to Tregs in colon adenocarcinoma and melanoma syngeneic tumour models." (PMID 40385641, 2025). "Clinically, therapeutic strategies targeting the tumor microenvironment (TME) such as CSF1R inhibition, CCR2/CCR5 blockade, and CD40 agonism show promise in preclinical and early-phase trials, especially when combined with immunotherapy." (PMID 40995363, 2025). "One study revealed that MDSC depletion (CSF-1R inhibitor) combined with BNCT extended mouse survival and promoted tumor immunity by reducing the number of tumor-associated macrophages and increasing the number of CD8+ T cells." (PMID 40313942, 2025). "Whereas, BLZ945 in the cytoplasm efficiently blocks intracellular-tyrosine-kinase of CSF1R and the resulting M2 polarization signaling pathway, allowing M1 macrophages to repress polarization to tumor-promoting M2-phenotype for long-lasting therapeutic effect." (PMID 40225567, 2025). "In murine PDAC the anti-tumour efficacy of M-CSF/CSF-1R blockers was strengthened when combined with immune checkpoint inhibitors, as tumour progression was reduced by >90%." (PMID 40385641, 2025). "In vivo, acute treatment of tumor-bearing mice with a CSF-1R blocking antibody significantly increased vascular tight junction stability, decreased TMEM doorway activity and TAVO events, as well as formation of CTCs." (PMID 40646332, 2025).
tumor (continued). "Future studies should include inhibition of tumor cell dissemination as a primary end point to evaluate the value of treatment with CSF-1R inhibitors." (PMID 40646332, 2025). "Anti-CSF-1R therapy or the standard-of-care treatment induces fibrosis, which supports tumor cell survival and dormancy within fibrotic niches." (PMID 40076738, 2025). "To further examine the effects of blocking CSF-1R signaling on macrophage-mediated trans-endothelial migration of tumor cells, we used our previously established in vitro trans-endothelial migration (iTEM) assay." (PMID 40646332, 2025). "Western blot analysis of tumor cells and murine bone marrow-derived macrophages (BMDMs) confirmed that CSF1R was expressed in monocyte-derived macrophages." (PMID 40538439, 2025). "These interactions maintain tumor-associated macrophage (TAM) viability and suppress therapeutic efficacy despite CSF1R inhibition." (PMID 40867316, 2025). "For example, using CSF1R inhibition to target macrophages (the predominant myeloid subset in tumours) have shown limited antitumour activity." (PMID 39633050, 2025). "The colony-stimulating factor-1 receptor and focal adhesion kinase offer a unique opportunity to mitigate tumor immune escape and enhance the efficacy of immunotherapy and conventional cytotoxic therapy by reprogramming the tumor microenvironment." (PMID 40539064, 2025). "Therapeutic strategies focus on depleting TAMs, blocking recruitment (e.g., CCR2/CSF1R inhibition), or repolarizing M2-like TAMs to anti-tumor M1 phenotypes." (PMID 40422244, 2025). "From a therapeutic perspective, strategies to reprogram TAMs toward an M1-like state—using checkpoint inhibitors, CSF-1R antagonists, or PI3Kγ inhibitors—aim to restore anti-tumor functions." (PMID 40724825, 2025). "As the intratumoural presence of CSF-1R+ macrophages correlates with poor survival in various tumour types, targeting CSF-1R signalling in TAMs represents an attractive strategy to eliminate or repolarize these cells." (PMID 40385641, 2025). "The long-term administration of BLZ945 (0.1 mg/mL), a control CSF1R inhibitor, exhibited tumor growth inhibition comparably to FF-10101 (0.1 mg/mL)." (PMID 39782686, 2025). "The pharmacological inhibition of anti-inflammatory macrophages through either Colony Stimulating Factor 1 Receptor (CSF-1R) or STAT6 pathways has significantly the decreased tumor burden in BCBM." (PMID 39858080, 2025). "Inhibiting CSF1R not only reduces the number of TAMs, but also reprograms the remaining ones to enhance antigen presentation and boost T-cell activation within the tumour environment." (PMID 40075571, 2025). "Preclinical models of GBM have shown that CSF-1R inhibition can significantly reduce TAMs, resulting in reduced tumor growth and improved survival outcomes." (PMID 40628732, 2025). "Efforts to improve response rates now focus on rational combinations: ICB plus chemotherapy, anti-TGF-β agents, CSF1R inhibitors (targeting TAMs), or intravesical agents that modulate the tumor immune microenvironment." (PMID 41256858, 2025). "As a result, blocking the CSF1/CSF1R axis changeds macrophage activation from tumor-promoting M2 to tumor-killing M1 phenotype 45." (PMID 40225567, 2025). "In CCA xenograft mouse models, CSF1R inhibition blocked monocyte‐to‐macrophage differentiation, decreased tumor cell proliferation and increased apoptosis, ultimately lowering tumor burden." (PMID 41143064, 2025). "Systemic therapies targeting the colony-stimulating factor 1 receptor (CSF1R) have resulted in positive tumor response, improved function, and decreased symptoms." (PMID 40392406, 2025). "In the same way as in the anti-CD47, we do this by modifying the value of the tumor killing parameter μ upon CSF-1R inhibition treatment." (PMID 40845580, 2025). "By releasing its ligand, CSF-1—potentially through tumor-mediated mechanisms—Csf-1R+ monocytes can differentiate into MDSCs, which then acquire immunosuppressive properties." (PMID 40674934, 2025).
tumor (continued). "Targeting key inflammatory mediators—such as the CCL2/CCR2 axis, CSF1R, or the IL-1β signaling pathway—has demonstrated promising anti-tumor effects in preclinical models." (PMID 40881678, 2025). "Acute blockade of CSF-1/CSF-1R signaling decreases macrophage VEGF-A secretion as well as TMEM doorway-associated vascular opening, tumor cell trans-endothelial migration, and dissemination." (PMID 40646332, 2025). "TAMs were polarized to a pro‐tumorigenic M2‐phenotype, expressing the CSF1R, which was observed at a higher frequency in splenic macrophages in tumor‐bearing mice." (PMID 40289661, 2025). "For example, agents targeting the CCL2/CCR2 axis have shown promise in reducing the recruitment of monocyte-derived TAMs, while inhibitors of colony-stimulating factor 1 receptor (CSF1R) blunt TAM support for tumor growth." (PMID 40330466, 2025). "A comprehensive characterization of CACs and their tumor microenvironment (TME) by scRNA-Seq identified an increase of specific macrophage subtypes in Mir34aΔMye CACs as well as elevated levels of Csf1r expression in Mir34aΔMye macrophages." (PMID 39425000, 2025). "Resistance to CSF-1R inhibitors is likely mediated through the interaction of insulin-like growth factor-1 (IGF-1) and tumor cell IGF-1 receptor (IGF-1R), causing an upregulation of the phosphoinositide 3-kinase (PI3K) pathway." (PMID 40427130, 2025). "BLZ945 and ARRY-382, which are also CSF1R inhibitors, have also been reported to remove TAMs and reduce tumor-promoting effects." (PMID 40940867, 2025). "Additionally, tumors may circumvent CSF1R blockade by recruiting alternative immunosuppressive cell types, including tumor-associated neutrophils (TANs), MDSCs, and tolerogenic dendritic cells, which collectively reinforce an immunosuppressive microenvironment." (PMID 40995363, 2025). "As in the CSF-1R blocking antibody experiments, blocking tumor-derived CSF-1 inhibited TMEM doorway activity, increased vascular integrity, and decreased dissemination of tumor cells as CTCs." (PMID 40646332, 2025). "Recent preclinical studies targeting CSF-1/CSF-1R have yielded promising results in several tumor models." (PMID 40646332, 2025). "By inhibiting the CSF1R axis, the function of TAMs can be downregulated, thereby favorably affecting the immune response within the tumor microenvironment." (PMID 40725764, 2025). "Studies have shown that radiotherapy combined with CSF-1R inhibitors exert synergistic effects through regulating macrophage polarization in the tumor microenvironment (TME), thereby improving tumor local control and enhancing anti-tumor immunity." (PMID 40007537, 2025). "New molecules and vaccines: Peptide vaccines against HER2-low and MUC1, a CSF1R inhibitor (altering the tumor microenvironment), and STING agonists are being investigated in clinical trials." (PMID 41150754, 2025). "CSF-1R inhibition using either BLZ945 or PLX3397 leads to tumor regression and enhanced survival in PDGF-driven proneural GBM mouse models by modifying macrophage polarization rather than depleting these cells." (PMID 40076738, 2025). "Based on the findings reported in the literature, we considered three main effects of CSF-1R inhibition:Increase in the phagocytic activity of anti-tumor macrophages." (PMID 40845580, 2025). "Through paracrine and autocrine signaling, tumor cells and associated stromal elements often produce high levels of CSF1 or IL-34, activating CSF1R on circulating myeloid precursors and promoting their migration into the tumor." (PMID 40821795, 2025). "In the tumor microenvironment (TME), macrophages are regulated by tumor-derived CSF-1, which binds to CSF-1R and promotes their survival and polarization into tumor-promoting phenotypes." (PMID 41462587, 2025). "As we show here, VEGF-A secretion from TMEM doorway macrophages can be triggered by tumor cell derived-CSF-1 binding to the CSF-1R on the macrophage." (PMID 40646332, 2025).
tumor (continued). "CSF1R Inhibitors: CSF1R inhibitors are used to deplete TAMs, which are often immunosuppressive, thereby enhancing the anti-tumour immune response." (PMID 40075571, 2025). "Our study revealed a correlation between MMP14 expression and various molecules regulating tumor immune cells, including CSF1R, HAVCR2, KDR, PDCD1LG2, TGFB1, CD70, CD86, and CXCL1." (PMID 40352589, 2025). "Small molecule inhibitors of the colony-stimulating factor 1 receptor (CSF1R) can alter the phenotype of the TAMs from M2 (pro-tumor) to M1 (anti-tumor)." (PMID 41041337, 2025). "This overexpression attracts cells of the mononuclear phagocyte lineage that express CSF1R into the tumor mass." (PMID 40677451, 2025). "The CSF-1R pathway critically influences macrophage polarization and contributes significantly to immunosuppression and tumor progression in GBM." (PMID 40628732, 2025). "Ex vivo data from patient-derived micro-tumors (PDMs) co-cultured with autologous tumor-infiltrating lymphocytes (TILs) corroborate these findings, with the combination of anti-CSF1R and anti-PD-1 promoting cytotoxic activity." (PMID 40867316, 2025). "An example is that USP1 and USP18 promote M2 polarization and tumour progression by deubiquitinating and stabilizing attractive receptors, including CXCR4 and CSF1R respectively in tumour-associated macrophage." (PMID 41562074, 2025). "This interaction is driven by a CSF-1/EGF paracrine loop, wherein tumor cells secrete CSF-1 (which attracts CSF-1R-expressing macrophages), while macrophages in turn secrete EGF (which attracts EGFR-expressing tumor cells)." (PMID 40646332, 2025). "Antibodies like cabiralizumab and emactuzumab, which target CSF-1R, aim to deplete these suppressive cells and reprogram the tumor microenvironment, thereby enhancing anti-tumor immune responses." (PMID 39833954, 2025). "Because of their roles in tumor progression, inhibitors that deplete macrophages such as colony stimulating factor 1 receptor (CSF1R) antibodies are currently being tested in clinics for cancer treatment." (PMID 40165290, 2025). "This highlights that depleting regulatory macrophages via CSF1R inhibition enhances cytotoxic macrophage activity, leading to robust tumor eradication when ATG9A-dependent membrane repair is impaired." (PMID 40595560, 2025). "Herein we noticed that CSF-1R inhibition altered phenotypes of cells other than myeloid cells, including a reduction in astrocyte activation and decreased tumor cell proliferation." (PMID 40760255, 2025). "In preclinical models of GB, CSF-1R inhibition had opposite effects on tumor growth depending on the tumor driver oncogene." (PMID 40642066, 2025). "Further researches are needed to achieve further understanding of the interaction between CSF-1/CSF-1R signaling pathway inhibitors and tumor radiotherapy and fibrosis." (PMID 40007537, 2025). "Macrophages are abundant immune cells in tumor microenvironment, and the CSF-1/IL-34/CSF1R axis often induces pro-tumorigenic macrophages." (PMID 39939179, 2025). "Combined with docetaxel, CSF-1R blockade enhances apoptosis and suppresses proliferation, providing strong rationale for combination approaches targeting both TAMs and tumor cells." (PMID 41228234, 2025). "The inhibition of CSF1R also resulted in low tumor proinflammatory chemokines and cytokine abundance." (PMID 40578365, 2025). "Therapeutic strategies targeting TAMs are rapidly evolving and include agents that block macrophage recruitment (e.g., CCR2 or CSF1R inhibitors), reprogram TAMs toward M1-like anti-tumor phenotypes, or deplete pro-tumoral populations." (PMID 40725175, 2025). "The use of the CSF-1R inhibitor PLX3397 effectively suppressed the BNCT-induced circulating M-MDSCs, as well as tumor-infiltrating M-MDSCs and tumor-associated macrophages, leading to an increase in CD8+ T cells." (PMID 41179690, 2025).